NOX1 (NADPH oxidase 1)
Diseases named in the same sentence as NOX1 in open-access papers (continued):
Sharing a sentence is not in itself a finding about the gene and the disease.
tumor (continued). "DEN-injected wild-type (WT) mice that received a NOX1 inhibitor ML171 developed fewer and smaller hepatic tumor nodules, compared to their vehicle-treated counterparts." (PMID 34571961, 2021). "The activation of the TLR4 signaling pathway in tumor cells by LPS can induce tumor proliferation through the COX-2 and EGFR pathways, and can promote metastasis via the NADPH oxidase 1-dependent ROS pathway." (PMID 33628591, 2021). "Despite NOX1 and NOX2 seeming to be inducers/promoters of HCC, recent findings postulate NOX4 as a tumor suppressor." (PMID 34571961, 2021). "Athymic mice with exogenous expression of NOX1 in wild-type fibroblasts of the NIH3T3 cell line presented noticeably enhanced cell growth and tumor formation." (PMID 34205998, 2021). "The role of TGF-β in tumorigenesis is controversial, since it induces both NOX1 and NOX4 expression in hepatocytes, acting as a tumor suppressor in the early phases of tumor development but also promoting invasiveness and metastasis in advanced cancer." (PMID 34204571, 2021). "This study evaluates the effect of pharmacological NOX1 inhibition on the development and progression of HCC and its effect on the tumor microenvironment." (PMID 33485364, 2021). "DEN-injected wild type (WT) mice that received the NOX-1 inhibitor ML171 also developed fewer and smaller hepatic tumor nodules, compared to their vehicle-treated counterparts." (PMID 33485364, 2021). "The NADPH oxidase family is one of the most relevant sources of ROS during cancer development NADPH oxidase 1 (NOX1) and Dual oxidase 2 (DUOX2) are examples of upregulated enzymes in tumor tissue." (PMID 33371444, 2020). "The overall process of apoptosis induction in CAP-treated tumor cells was completely inhibited when either scavenging of 1O2 by histidine, decomposition of ONOO− by FeTPPS, or inhibition of NOX1 by AEBSF continued over the whole time of the experiment." (PMID 31558835, 2019). "In conclusion, combination treatment with a NOX1 inhibitor and anti-PD1 antibody was more effective for blocking tumor growth than single agent therapy, and the effect was confirmed in NOX1-deficient mice." (PMID 31249132, 2019). "We previously showed that NADPH oxidase organizer 1 (Noxo1), a component of NADPH oxidase 1 (NOX1), is a TNF-α-induced tumor-promoting factor in gastric tumorigenesis." (PMID 30700829, 2019). "This highly dynamic process is essentially driven by NOX1 and NOS of the tumor cells, and finally leads to intercellular RONS-driven apoptosis induction." (PMID 31558835, 2019). "Consistent with the in vitro studies, NOX1 and NOX4 were greatly upregulated in tumor xenografts treated with PJ-34." (PMID 29684820, 2018). "In the tumour microenvironment, cancer cells produce high levels of ROS deriving from mitochondrial dysfunction, upregulation of NADPH oxidase 1 (NOX-1) and NADPH oxidase 4 (NOX-4), and alterations of antioxidant enzymes." (PMID 29967776, 2018). "Tumor cells, as known, generate extracellular superoxide anions with the participation of NADPH Oxidase 1 (NOX1)." (PMID 27270647, 2016). "Nox1 is a homolog of the catalytic subunit of the superoxide-generating NADPH-oxidase that is often overexpressed in tumors and is involved in tumor progression and angiogenesis." (PMID 22889244, 2012). "We previously demonstrated that NOX1 pharmacologic inhibition did not affect tumor angiogenesis in immunodeficient mice." (PMID 38137406, 2023). "Regarding the pro-angiogenic and lymphangiogenic roles of NOX1 and ADAM17 in CRC, we hypothesized that sMCAM could act as a lymphangiogenic growth factor and promote tumor lymphangiogenesis." (PMID 38137406, 2023). "We wonder whether combining GPX4, NOX1, and FACL4 could complementarily present tumor ferroptosis status in CRC." (PMID 35855531, 2023). "Interestingly, the pharmacologic inhibition of NOX1, using a selective NOX1 inhibitor (GKT771) and NOX1 genetic ablation in mice, demonstrated potent anti-tumor and anti-angiogenic activities." (PMID 38137406, 2023).
tumor (continued). "This study for the first time demonstrated that HCC cells utilized OPN to generate ROS for tumor progression, and disruption of OPN/NOX1 axis might be a promising therapeutic strategy for HCC." (PMID 35418176, 2022). "Indeed, SHMT1 acts as tumor suppressor as inhibits HCC metastasis, EMT and MMP2 by repressing NOX1-derived ROS production." (PMID 34571961, 2021). "Despite the opposite role of NOX1 and NOX4 in HCC (the first one promoting and the second one suppressing tumor progression), the fact that most of the liver tumor cells express low levels of NOX4 facilitates the use of general NOX inhibitors as promising tools in the treatment of liver cancer." (PMID 34571961, 2021). "Besides NOX1, NOX2-derived ROS are also involved in TLR2-dependent M2 macrophage polarization, supporting tumor growth." (PMID 34571961, 2021). "In comparison to non-malignant cells, the outer membrane of tumor cells was characterized based on NOX1, SOD, and MAC expression." (PMID 33477494, 2021). "Despite empirical evidence that NOX1 is upregulated in certain CRC cell lines and in a modest number of human tumor specimens, a detailed understanding of the prevalence and distribution of NOX1 in CRC is lacking." (PMID 32428030, 2020). "NOX1 and other NOX isoforms are involved in promoting tumor development." (PMID 31249132, 2019). "When pretreatment of tumor cells with CAP and the subsequent 25 min incubation step were performed in the presence of AEBSF (open circles), and thus the contribution of NOX1-dependent generation of secondary 1O2 was prevented, subsequent bystander signaling of this population was quite low." (PMID 31558835, 2019). "It took into account that the outer membrane of tumor cells, in contrast to nonmalignant cells, is characterized by the expression of NOX1, catalase and SOD5,6,9,12,15,53,54." (PMID 31578342, 2019). "The first important finding of the present work is that tumor NOX1 is not critical for the overall in vivoantitumor effects of GKT771." (PMID 31249132, 2019). "As a result, tumor cells treated with siRNA directed towards NOX1 show the phenotype of nonmalignant cells with respect to their intercellular redox biology, i." (PMID 31578342, 2019). "Both molecular species are constantly generated by tumor cells, due to their active NOX1 and NOS, and are no longer decomposed at sites of catalase that has been inactivated by primary 1O2." (PMID 31558835, 2019). "In addition, numerous inflammatory cytokines such as INF-γ affect the expression levels of NOX1, and INF-γ itself is involved in the recruitment of hemopoietic cells, suggesting that NOX1 contributes to immune cell recruitment in the tumor microenvironment." (PMID 31249132, 2019). "In particular, this analysis evidenced strongly up-modulated NADPH oxidase 1 (NOX1) transcript levels in tumor cells lacking LKB1." (PMID 29915721, 2018). "Our study provides evidence that NOX2 oxidase promotes tumour angiogenesis, however, we are not ruling out a contribution from other NOX1 isoforms including the NOX1 and NOX4 oxidases." (PMID 30459931, 2018). "The depletion of NOX1 and NOX4 in tumor xenografts was confirmed by Western blot." (PMID 29684820, 2018). "Except for a modest increase in TUNEL positivity in serum-starved 6A cells at the G1/S interface, the increase in tumor cell doubling time observed following NOX1 inhibition was not accompanied by a substantive degree of apoptosis." (PMID 28330872, 2017). "The 80–90% decrease in NOX1 expression achieved by RNAi produced a significant decline in ROS production and a G1/S block that translated into a 2–3-fold increase in tumor cell doubling time without increased apoptosis." (PMID 28330872, 2017). "Increased generation of Nox1-derived ROS is functionally required for Ras transformation phenotypes, upregulation of vascular endothelial growth factor (VEGF), tumor progression and tumor cell migration." (PMID 26760964, 2016).
tumor (continued). "We also isolated the tumor tissue (MCF-7 xenograft) from animals treated with cambogin (10 mg/kg) for 35 days, consistent with the in vitro data, cambogin indeed enhanced the interaction of NOX1 and p22phoxin vivo." (PMID 27418140, 2016). "As for all the oxidative tumor cells tested in this study, they did express Nox1, Nox2, and Nox4 but did not activate the NF-κB pathway in response to lactate." (PMID 26528183, 2015). "A correlation between NOX1 levels and the tumor grade/stage was observed in bladder cancer, though not in colon cancer." (PMID 25806803, 2015). "Induction of angiogenesis may be due to NOX1 expression by LLC1 tumors, producing high amounts of ROS in the tumor microenvironment and modulating endothelial cell functions." (PMID 21326871, 2011). "It has been shown that excess Zn ions in tumor cells can induce ROS production via two pathways: leakage of the aerobic respiratory electron chain and oxidation of nicotinamide adenine dinucleotide phosphate (NADPH) by NADPH oxidase 1 Gene (NOX1) in mitochondria." (PMID 40486836, 2025). "As NOX1 is expressed by tumor cells and host cells, in particular endothelial cells, and regulates ADAM17 activation and sMCAM release, we next assessed whether ADAM17 or sMCAM tumor-promoting functions would act downstream of NOX1." (PMID 38137406, 2023). "In order to further investigate the role of NOX1 and its potential as a therapeutic target in the treatment of HCC, we studied the effect of the NOX1 inhibitor GKT771 (provided by Genkyotex) in a DEN-induced HCC mouse model, with specific focus on the inflammatory tumor microenvironment (TME)." (PMID 33485364, 2021). "A study found that mice lacking NOX1 expression demonstrated impaired angiogenesis and tumor growth, lending support that NOX1 might be crucial in angiogenesis and tumor growth." (PMID 33187272, 2020). "Hence, in the Lewis lung carcinoma model, wild-type and NOX1/NOX2 double-knockout mice showed a similar degree of TAM infiltration, while the content of M2-TAMs was reduced in the double-knockout mice along with reduced tumor growth." (PMID 33312338, 2020). "However, although GKT771 reduced the plasma concentrations of PLGF and VEGF-A and suppressed blood vessel and lymphatic angiogenesis, this was not the main mechanism by which NOX1 suppressed tumor growth." (PMID 31249132, 2019). "Therefore, when NOX1, that discriminates malignant cells from nonmalignant cells, is inhibited in tumor cells, they loose their sensitivity for apoptosis induction mediated by singlet oxygen." (PMID 26225731, 2015). "Indeed, expression of NOX molecules are induced in vascular endothelium and in tumor cells during the angiogenic switch and inhibition of NOX1 in both the host and the tumor cells using the potent NOX1 inhibitor GKT136901, results in reduced tumor angiogenesis and tumor growth." (PMID 21326871, 2011). "Furthermore, TMI-5 displays potential additive anti-tumor properties independent of host NOX1." (PMID 38137406, 2023). "However, the pathways which are controlled by NOX1 in tumor cells are not well defined." (PMID 25806803, 2015). "Furthermore, MMPs may affect the redox conditions in the tumor microenvironment and vice versa, as, for example, MMP-2 and MMP-9 are upregulated by NOX/ROS-dependent NFκB activity, whereas MMP-3 activation induces mitochondrial ROS production and NADPH oxidase 1 (Nox1)." (PMID 33379400, 2020). "In these experiments, NOX1-transfected cells (10-fold over-expression of NOX-1 in NIH3T3 fibroblasts) induced increased growth and transformation despite a restricted production of superoxide anions, revealing that high levels of ROS are not responsible for the initiation of tumor processes." (PMID 34205998, 2021).
cancer (96 papers, 2010 to 2026). A tumor composed of atypical neoplastic, often pleomorphic cells that invade other tissues. "In gallbladder cancer have been reported an increased expression of NOX1 in cancer-associated fibroblasts, correlating with an invasive phenotype and poor prognosis." (PMID 39696702, 2024). "NOS31, another selective inhibitor derived from Streptomyces sp., inhibits the growth of cancer cells in various types of cancer associated with increased expression of NOX1, including stomach and colon cancer cells." (PMID 38370049, 2024). "Based on the TCGA database, we systematically evaluated the expression patterns and mutational frequency of NOX1 in pan-carcinoma." (PMID 37679792, 2023). "NADPH oxidase enzymes (Nox1, Nox2, and Nox4), located in lipid rafts, have been found associated with growth promotion in cancer." (PMID 33585438, 2020). "The NADPH oxidase NOX1-stimulated local cancer cell migration along collagen I fibers depends on the NADPH oxidase NOX1-induced oxidative burst caused by AA-activated 12-LOX, which results in phosphorylation of PKC." (PMID 29478325, 2019). "Among a set of 20 genes involved in redox homeostasis, NOX1 transcript was consistently down-regulated following forced expression of LKB1 cDNA in LKB1-deficient cancer cells." (PMID 29915721, 2018). "In this regard, analysis of NSCLC cancer cell lines showed increased NOX1 mRNA levels in cell lines bearing LKB1 and KRAS mutations." (PMID 29915721, 2018). "Over expression of NOX1 can result in excessive generation of reactive oxygen species linked to cancer." (PMID 25423035, 2014). "Activation of angiogenesis has been associated with over expression of NOX1 in aggressive carcinomas." (PMID 25423035, 2014). "Once LAB colonizes in GC, it can potentially promote GC via 4 mechanisms: 1) via impact the release of interleukin-1β/17 A/22, 2) via IL-17RC/NF-ᴋB/NOX1 pathway, 3) via gastric inflammatory and cancer-associated genes TNF-α/Ptger4/Tgf-β, 4) via N-nitroso compounds and 5) ROS." (PMID 38075398, 2024). "The blocking of NOX1 functions selectively impairs cancer cells with mitochondrial dysfunction, leading to a decrease in cellular glycolysis, a loss of cell viability, and an inhibition of cancer growth in vivo, suggesting that NOX1 is a potential novel target for cancer treatment." (PMID 36768405, 2023). "NOX1 is highly expressed with a low mutational frequency in pan-carcinoma." (PMID 37679792, 2023). "Furthermore, overexpression of the protein Nox1 producing reactive oxygen species can cause cellular transformation and tumorigenesis, confirming the participation of ROS in cancer development." (PMID 34638706, 2021). "However, the mechanism(s) underlying increased NOX1 expression in malignant tumors or chronic inflammatory states involving the intestine are poorly characterized." (PMID 28498822, 2017). "Among the key contributors to ROS generation are the NADPH oxidase (NOX) enzymes, particularly NOX1, which is often upregulated in various cancer types." (PMID 40427384, 2025). "NADPH oxidase 4 (NOX4), a downstream mediator of the TGF-β signalling pathway, is strictly expressed in cancer-associated fibroblasts (CAF) of iCCA and acts in concert with NOX1 to regulate CAF functions." (PMID 40820091, 2025). "The seven transmembrane NOX family, including dual oxidases 1 and 2 and NOX1-5, generate superoxide anion radicals and play potential roles in various cancers." (PMID 39796030, 2024). "The relatively low expression of Nox1 is unexpected given the well-described role of Nox1 in cancer." (PMID 39334772, 2024). "In inflammatory settings, TNFα induces NoxO1 expression and subsequent Nox1-dependent ROS formation, which results in the enhanced proliferation of stomach epithelial cells and eventually cancer formation." (PMID 39334772, 2024). "NOX1 is proposed to be involved in the GI tract innate immune responses and in GI carcinogenesis, being overexpressed in cancers affecting the large and small intestine." (PMID 37516013, 2023).
cancer (continued). "CK18 accumulation induced by Nox1 is consistent with the persistence of fetal-type CK18 protein in many epithelial carcinomas." (PMID 36902094, 2023). "All of these findings together suggested that OPN promoted cancer growth, ROS production, NOX1 expression, and phosphorylation of JAK2/STAT3 in vivo." (PMID 35418176, 2022). "This is consistent with previous studies showing that NOX1 favors ferroptosis in certain cancer cells." (PMID 36274088, 2022). "Although multiple genes, such as ACSL4, PTGS2, NOX1, GPX4, FTH1, and SLC7A11, have been shown to be associated with ferroptosis, it is unclear how ferroptosis is genetically programmed in cancers." (PMID 35321435, 2022). "Accumulating evidence suggests that NOX1 is involved in the occurrence and development of a variety of cancers." (PMID 33968728, 2021). "NOX1, 2, 4 and 5, localized in endothelial cells participate in every stage of angiogenesis (Part 6.2.5), and play a crucial role in cancer-induced blood vessel formation." (PMID 34205998, 2021). "As a product of NOX1, ROS levels were essential regulators in cancer growth, metastasis, and other malignant behaviors." (PMID 33968728, 2021). "In this study, we systematically assessed the prevalence of NOX1 in multiple human cancers using appropriate samples sizes to draw statistically robust conclusions." (PMID 32428030, 2020). "Other studies have emphasized the role of oxidative stress and NOX1 proliferate malignant cells in the early stages of cancer." (PMID 32856850, 2020). "The extracellular superoxide anion-generating enzyme NOX1 has been connected to cancer cell proliferation (i.e., the growth of cancer cells), and the generation of superoxide anions by several cancer cell lines has been reported." (PMID 33096638, 2020). "The perturbation of the cytoskeleton by either UM0112176 or in combination with apocynin is consistent with NOX1-dependent ROS production for proper cytoskeletal organization in these cancer cells." (PMID 31558701, 2019). "Taken together, these findings suggest that NOX1 is a promising therapeutic target for the management of immune/inflammatory events in cancer and vascular pathologies." (PMID 31249132, 2019). "The lack of discernable changes in astrocytes agrees with the virtual absence of NOX1 in these cells and reinforces the importance of ROS production by NOX1 in cancer cells for proper cytoskeletal organization." (PMID 31558701, 2019). "It has been demonstrated that NOX1 participates in epithelial–mesenchymal transition, a process facilitating cancer cell invasion." (PMID 31558701, 2019). "The observations that the therapeutic effects of GKT771 are dissociated from NOX1 expression levels in cancer cells seems at odd with previously published data." (PMID 31249132, 2019). "Overexpression of NOX1 in fibroblasts and in carcinoma cells induces an angiogenic switch mediated by increased production of VEGF and MMPs." (PMID 30459931, 2018). "The role of NOX5 is less understood than those of NOX1, 2, and 4, but it is also reported to play a significant function in cancer." (PMID 28626501, 2017). "We are thus showing for the first time an inversion of regulation of Nox1 by calpains according to the resistance status of our cancer cells." (PMID 29262595, 2017). "Because of these facts, the function of NOX1 in human cancer has been focused on among the NOX family members." (PMID 29065504, 2017). "NOX1 and NOX4, and the common subunit P22PHOX (encoded by CYBA) are, in contrast, activated in cancer cells and have been associated with keratinocyte-specific activity." (PMID 28122935, 2017).